BRCA1 (BRCA1 DNA repair associated)
Diseases named in the same sentence as BRCA1 in open-access papers (continued):
Sharing a sentence is not in itself a finding about the gene and the disease.
breast cancer (continued). "Targeted therapy has advanced significantly with PARP inhibitors in the treatment of breast cancer, especially for patients with BRCA1/2 mutations." (PMID 40141415, 2025). "An elevated risk of breast cancer, ovarian cancer, as well as other cancers like prostatic, pancreatic, and melanoma, is a characteristic of BRCA1/2-associated HBOC." (PMID 40286038, 2025). "Such variants are associated with a risk of breast cancer to age 80 of 72% for BRCA1 variant carriers and 69% for BRCA2 variant carriers, while the general population has a lifetime risk of 12%." (PMID 40445415, 2025). "In summary, we conclude that although risk of developing breast cancer is different for specific PVs, it is premature to use type and location of PVs to stratify BRCA1 carriers about their personal cancer risk." (PMID 41440233, 2025). "In BRCA1 mutation carriers, there is an increased risk for the development of breast cancer, conferred by the functional inactivation of the tumor suppressor role that the BRCA1 gene plays." (PMID 39941709, 2025). "Breast cancer-specific studies have shown that general pathogenicity predictors underestimate the relevance of BRCA1/BRCA2-associated variants, leading to inconsistent classification outcomes." (PMID 41263939, 2025). "The life-time risk of breast cancer for carriers of BRCA1 and BRCA2 pathogenic variants is about 65% and 45%, respectively." (PMID 40296163, 2025). "This is in parallel with variants in genes implicated in hereditary breast cancer including the ‘high risk’ genes BRCA1, BRCA2, and PALB2 and ‘moderate risk’ genes CHEK2 and ATM." (PMID 41327266, 2025). "Second primary cancer (SPC) risks after breast cancer (BC) in BRCA1/BRCA2 pathogenic variant (PV) carriers are uncertain." (PMID 39475295, 2025). "The percentage of breast cancer patients that are positive for BRCA1 or BRCA2 mutations varies depending on strategy utilized and the population tested." (PMID 41568010, 2025). "Pathogenic mutations in BRCA1/2 genes impair DNA damage repair mechanisms, resulting in genomic instability and significantly increasing the risk of breast cancer, particularly in mutation carriers who develop the disease before the age of 70." (PMID 39996778, 2025). "Collectively, these in vivo experiments have provided evidence that BRCA1-associated breast cancer arises from luminal progenitors and that BRCA1 appears to influence the cell fate specification of luminal progenitor cells." (PMID 41347767, 2025). "The 2018 Japanese Breast Cancer Society guideline recommended adding contrast-enhanced breast MRI to annual mammography for BRCA1/2 mutation carriers." (PMID 41083355, 2025). "Women with germline BRCA1 variants are estimated to have 60%–72% risk of breast cancer to age 70, while those with BRCA2 variants are estimated to have 55%–88% risk." (PMID 39907309, 2025). "It is noted that the poor prognosis associated with Cezannelow or Ube2Shigh tumors are more prominent in ER+ breast tumors, whereas most BRCA1-mutated breast cancers are ER-." (PMID 41359628, 2025). "While one-third of breast cancer cases show familial clustering, only 5–10% are due to high-penetrance mutations in genes such as BRCA1 and BRCA2." (PMID 40243654, 2025). "In this prospective cohort of 3677 unaffected BRCA1 carriers, the annual breast cancer risk from age 30 to 75 was 2.1%, with a 15-year cumulative risk of 24.8%." (PMID 41440233, 2025).
breast cancer (continued). "Approximately 12% of breast cancers in the Ashkenazi Jewish population are attributable to mutations in the BRCA1 or BRCA2 gene." (PMID 39941369, 2025). "About two-thirds of breast cancers associated with pathogenic germline variants in BRCA1 show triple-negative subtype, while a HR+/HER2- subtype is identified in 60–70% of patients with pathogenic germline variants of the BRCA2 gene." (PMID 40557948, 2025). "The average age at diagnosis for BRCA1 carriers is between 41 and 50 years, highlighting the need for high-risk breast cancer screening, including the consideration of early screening, and the addition of breast MRI in this population." (PMID 40155574, 2025). "PARP inhibitors are targeted therapeutic agents designed to impair DNA damage repair, and are primarily used in breast cancer patients with BRCA1/2 mutations." (PMID 41219968, 2025). "In this study, we introduce MAIGGT, the first interpretable multi‐modal deep learning framework for predicting pathogenic germline BRCA1/2 mutations in breast cancer patients using routine EHR and histology images." (PMID 40439693, 2025). "Our study aimed to uncover disease-causing variants in BRCA1 among female breast cancer patients belonging to the Abbottabad district, Pakistan." (PMID 40904409, 2025). "Combined with the extremely high risk of breast cancer associated with these pathogenic variants (40–90%), the high prevalence of BRCA1/2 in Nigeria underscores the critical role of genetic testing for early cancer detection and treatment." (PMID 40390103, 2025). "A significant increase in the incidence of breast cancer and ovarian cancer is observed when BRCA1 is deleted or mutated." (PMID 39997609, 2025). "With SGE able to accurately predict cancer risk and enrichment of LoF BARD1 missense variants in breast cancer cases, we provide additional evidence that BRCA1 and BARD1’s role in HDR is required for tumor suppression in humans." (PMID 41282735, 2025). "Our results suggest that BCT can be considered a safe treatment option for patients with breast cancer carrying BRCA1 or BRCA2 pathogenic variants." (PMID 40366658, 2025). "Linc-ROR inhibits BRCA1 expression, promoting a mesenchymal phenotype and increasing breast cancer metastasis risk." (PMID 39997609, 2025). "Recently, a prospective study discussed the potential risk of developing breast cancer with the synergistic effect of a mutation in the BRCA1 gene, high copper levels, and a high Cu/Zn ratio in the blood serum." (PMID 40429927, 2025). "In the United States, Angelina Jolie’s decision to share her experience with the increased risk of breast and ovarian cancer due to BRCA1 gene mutations has improved public awareness of the disease and increased genetic testing and breast cancer screening." (PMID 40036529, 2025). "In our subgroup analysis of 89 T1N0 breast cancers, 56% of BRCA1-associated cases were TNBC compared to only 18% of BRCA2 and PALB2-associated cases." (PMID 40275390, 2025). "Carriers of one of the three BRCA1 founder mutations are observed in the Polish population, and their cumulative annual risk of developing breast cancer has been estimated at 1.78%4." (PMID 39863726, 2025). "Approximately, two thirds of the BRCA1/2 mutations found in breast cancer are germline mutations, whereas the remaining third are somatic." (PMID 38867388, 2025).
breast cancer (continued). "The French Liber Trial compared the efficacy of letrozole compared to a placebo for primary prevention of breast cancer in postmenopausal women carrying BRCA1 or BRCA2 P/LP variants." (PMID 39858629, 2025). "Family history plays a critical role in breast cancer risk, as germline mutations in the tumor suppressor genes BRCA1 and BRCA2 are strongly associated with an inherited predisposition to the disease." (PMID 39997609, 2025). "This study describes the frequency and type of variants in hereditary cancer genes associated with breast cancer detected by the next-generation sequencing of a panel of 111 hereditary cancer genes, including BRCA1 and BRCA2." (PMID 40259910, 2025). "In OlympiAD study, Olaparib significantly prolonged progression-free survival (PFS) of patients with germline BRCA1/2 mutated HER2-negative advanced breast cancer compared to chemotherapy (7.0 months vs. 4.2 months)." (PMID 41293157, 2025). "We characterized breast cancer risk associated with established risk factors among WHI participants who carry PVs in BRCA1/2, ATM, CHEK2, and PALB2." (PMID 40298171, 2025). "According to the National Comprehensive Cancer Network, more than 60% of women with a pathogenic germline mutation in BRCA1 or BRCA2 are projected to develop breast cancer over the course of their lifetime." (PMID 41002733, 2025). "For example, CDDO‐imidazolide has been found to induce G2/M cell cycle arrest in BRCA1‐mutated breast cancer cells, and CDDO‐Me has been found to significantly arrest K562 cells in the G2/M and S phases." (PMID 40439120, 2025). "Approximately 3% of breast cancers (approximately 7,500 women per year) result from inherited mutations in the BRCA1 and BRCA2 genes." (PMID 40303990, 2025). "In the BRCA1 P/LP variant group, five of the eight women who developed breast cancer were on tamoxifen, while three were in the placebo group (RR 1.67; 95% CI 0.32–10.7)." (PMID 39858629, 2025). "Breast cancer gene 1 (BRCA1) is a tumor suppressor gene essential for DNA repair, and its mutations are linked to aggressive breast cancers with poor prognosis." (PMID 41148817, 2025). "We report on penetrance and breast cancer risk–modifying factors for PVs in BRCA1/2, ATM, CHEK2, and PALB2 among WHI participants." (PMID 40298171, 2025). "Denosumab shows promise in preventing BRCA1-mutated breast cancer by inhibiting bone metastasis and providing additional anticancer effects, significantly improving patient prognosis." (PMID 41225545, 2025). "Meanwhile, it was found that some gene markers associated with breast cancer were also present in the yellow module, such as BRCA1 and CCNB1." (PMID 41394782, 2025). "Over 64% of NPCs are deficient in a pathway that depends on the breast cancer susceptibility genes BRCA1 and BRCA2, which accurately repair DNA crosslinks and breaks via the homologous recombination pathway." (PMID 39885374, 2025). "Research has identified several key characteristics of germline BRCA1/2 pathogenic variants (PVs) in relation to breast cancer." (PMID 40405286, 2025). "This review examines the roles of lincRNAs associated with BRCA1 in the landscape of breast cancer, highlighting the potential avenues for future research and clinical applications." (PMID 39997609, 2025). "Breast cancer in women under the age of 30 demonstrates a high Ki-67 proliferation index, high BRCA1/2 pathogenic variant rates, and low estrogen receptor (ER) expression, contributing to advanced-stage presentation." (PMID 41531577, 2025). "The impact of a germline BRCA1/2 pathogenic variant (gBRCApv) on baseline or late post-treatment AMH concentrations in breast cancer patients has been extensively studied, yielding mixed conclusions." (PMID 40220108, 2025).
breast cancer (continued). "Previous studies have shown that approximately 5% of breast cancer cases are associated with BRCA1, BRCA2, and other high-penetrance gene mutations." (PMID 40666442, 2025). "This contrasts with MM1 domain mutations identified in non-BRCA1/2 breast cancer families, which show the opposite pattern-disrupted FANCD2:FANCI monoubiquitination but intact ATPase activity." (PMID 40447800, 2025). "Wang and colleagues also demonstrated that estrogen can promote EMT in a subset of Brca1-deficient breast cancer cells through an ER-independent signaling pathway." (PMID 41228249, 2025). "A prospective study evaluated the association between annual MRI surveillance and the risk of breast cancer mortality among women carrying BRCA1 or BRCA2 P/LP variants." (PMID 39858629, 2025). "Another study reported BRCA1/2 mutations in 25% of high-risk breast cancer patients with NMSC, with BRCA1 being more prevalent, but the small sample size of only 16 cases limits its significance." (PMID 41331641, 2025). "Regarding the connection between the BRCA1 DNA repair associated (BRCA1) germ-line mutations and basal-like breast cancer, there is mounting evidence that basal-like breast tumors and the BRCA1 pathway are related." (PMID 40141415, 2025). "By the age of 70, female carriers of mutations in either Brca1 or Brca2 had a 60–80% likelihood of developing breast cancer." (PMID 40153121, 2025). "The breast cancers are associated with three types of mutations: BRCA1, BRCA2, and Sporadic mutations." (PMID 41542084, 2025). "In BRCA1 P/LP variant carriers, the authors observed a reduction of 32% in breast cancer risk (OR 0.68; 95% CI 0.52–0.91; p = 0.008) for breastfeeding for at least one year and of 49% (OR 0.51; 95% CI 0.35–0.74) for over two years of breastfeeding." (PMID 39858629, 2025). "This study aimed to compare PROs in women carriers of P/LP variants in BRCA1/2 according to their choice of breast cancer risk management." (PMID 40445415, 2025). "Among breast cancer patients with germline BRCA1/2 mutations, the PARP inhibitors olaparib and talazoparib have demonstrated clinical efficacy in the metastatic setting, as confirmed by the OlympiAD and EMBRACA trials, respectively." (PMID 41300964, 2025). "Talazoparib was evaluated for treating advanced HER2− breast cancer with germline BRCA1/2 mutations from the perspective of the health sector in China and in the United States." (PMID 41008856, 2025). "To test this, we generated CASP3 + 7 DKD in the BRCA1-deficient SUM149PT breast cancer cells and assessed their viability by the crystal violet assay." (PMID 39982959, 2025). "Breast cancer patients carrying BRCA1/2 mutations are typically responsive to platinum-based chemotherapy as well as radiation therapy and PARP inhibitors due to their impaired HRR capacity." (PMID 40612353, 2025). "Although BRCA1 mutations account for only 2–3% of all breast cancer diagnoses in the general population, they contribute to 40–45% of the hereditary breast cancer cases." (PMID 39997609, 2025). "Our results align with previous studies examining the relationship between OC use and breast cancer risk in BRCA1 and BRCA2 mutation carriers." (PMID 41327462, 2025). "It has been reported that patients with pancreatic cancer carry rare germline deleterious variants of breast cancer susceptibility genes such as BRCA1, BRCA2, PALB2, and ATM." (PMID 38204267, 2025). "Among females who received chest radiation before age 30, the cumulative incidence of breast cancer approaches 20% by mid-adulthood, a risk comparable to that of BRCA1 mutation carriers." (PMID 41393746, 2025). "Background and Objectives: Most of the research on the role of the BRCA1 gene in breast cancer is focused on monoallelic germline alterations and loss of heterozygosity in tumors." (PMID 40870889, 2025).
breast cancer (continued). "In our study, rs799905 was detected in 18 out of 47 (38%) BC patients with detectable methylation and low expression of BRCA1; subsequently it was tested in 3 study groups to evaluate a possible association with breast cancer." (PMID 40495194, 2025). "Specifically, breast cancers in patients with BRCA1 mutations tend to exhibit a benign appearance and display more circumscribed margins and rim enhancement compared to those with BRCA2 mutations." (PMID 40942929, 2025). "It accounts for approximately 15–20% of all breast cancers and is more prevalent among younger women, African American women, and those with BRCA1 mutations." (PMID 40034665, 2025). "A variant was identified and genotyped in multiple patient groups, including 336 BRCA1 methylation-positive women, 1898 unselected breast cancer cases, 2234 healthy controls, and 309 BRCA1 pathogenic variant (PV) carriers." (PMID 40495194, 2025). "BRCA-related cancer: The USPSTF recommends screening for mutations in the breast cancer susceptibility genes BRCA1 and BRCA2 in women considered at risk (grade B)." (PMID 40177455, 2025). "TNBC exhibits a worse clinical course with respect to other breast cancer subtypes and occurs more frequently in patients carrying BRCA1 mutations." (PMID 41373619, 2025). "Our study was based on global transcriptome sequencing of breast cancer tissue samples to identify differentially expressed genes and signaling pathways associated with monoallelic somatic BRCA1 inactivation." (PMID 40870889, 2025). "This cohort study evaluates the long-term outcomes of breast-conserving treatment (BCT) on recurrence and survival in patients with breast cancer with BRCA1 and BRCA2 pathogenic variants." (PMID 40366658, 2025). "TNBC accounts for 10–15% of breast cancer cases and is more prevalent in younger women, especially those carrying BRCA1 mutations." (PMID 40806457, 2025). "XZP-7797 also showed good PK and ADME properties and good BBB penetration in a mouse model and demonstrated significant efficacy in breast cancer cell lines, a BRCA1-mutated breast cancer CDX model, and a pancreatic cancer CDX model." (PMID 40521389, 2025). "In breast cancer, BRCA1 mutations disrupt homologous recombination (HR) repair processes, leading to increased genomic instability and the accumulation of DNA double-strand breaks (DSBs)." (PMID 39997609, 2025). "Roughly 5–10% of breast cancers are related to inherited cancer-causing genes called BRCA1/2 pathogenic germline variants (PGVs)." (PMID 40123843, 2025). "Research has shown that hereditary factors are involved in the occurrence and progression of breast cancer, with BRCA1/2 gene mutations linked to familial breast cancer cases." (PMID 39996778, 2025). "By the time they are 70, a person with a BRCA1 mutation has a 65%–85% risk of developing breast cancer." (PMID 39812114, 2025). "Female carriers of BRCA1 mutations have a 70% lifetime risk of developing breast cancer by the age of 80." (PMID 39997609, 2025). "A critical factor influencing treatment response in breast cancer is the presence of pathogenic variants (PVs) in the BRCA genes (BRCA1 and BRCA2)." (PMID 40427118, 2025). "This difference can mainly be attributed to the highly increased lifetime risk of developing breast cancer for women, which is comparable to BRCA1/2 PV carriers." (PMID 40407579, 2025). "This clinical trial will include advanced/relapsed ovarian, breast, pancreatic, and prostate cancer patients who can be treated with PARPis and HER2-negative breast cancer patients with BRCA1/2, PALB2, RAD51C, and RAD51D mutations." (PMID 40521389, 2025). "BRCA1 (BRCA1 DNA Repair Associated, also known as Breast Cancer Type 1 Susceptibility Protein) and BRCA2 (BRCA2 DNA Repair Associated, or Breast Cancer Type 2 Susceptibility Protein) encode proteins that function as E3 ubiquitin ligases." (PMID 41008855, 2025).